CDX1 (caudal type homeobox 1)
Diseases named in the same sentence as CDX1 in open-access papers (continued):
Sharing a sentence is not in itself a finding about the gene and the disease.
cancer (17 papers, 2009 to 2025). A tumor composed of atypical neoplastic, often pleomorphic cells that invade other tissues. "Coexpression data from the Cancer Cell Line Encyclopedia supported this association partly and showed CDX1 positively correlated with FUT3 (Pearson's correlation 0.63)." (PMID 26537799, 2016). "Besides fucosylation, we found that high CDX1 mRNA expression in cancer cell lines also associated with low levels of sialylation and galactosylation and high levels of bisection on N-glycans." (PMID 30909444, 2019). "Finally, correlation of CRC cell line glycosylation features with cancer cell markers and phenotypes revealed an association between highly fucosylated glycans and CDX1 and/or villin mRNA expression that both correlate with cell differentiation." (PMID 26537799, 2016). "Our findings suggest that CDX1/2 cooperatively suppressed colonic tumorigenesis and cancer stemness by antagonizing β-catenin via the DSIF and PAF1 complexes." (PMID 40399276, 2025). "The mean CDX1 expression in the submucosal cancer tissue of the extragastric recurrence group (−4.6 ± 2.0) was significantly lower than that in the control group (−2.4 ± 1.8) (p = 0.025)." (PMID 35683460, 2022). "In the extragastric recurrence group, the expression of CDX1 in the submucosal cancer tissue was significantly lower than the expression observed in the mucosal layer (−2.4 ± 1.8 vs. −2.6 ± 2.0, p = 0.047)." (PMID 35683460, 2022). "Although glycosylation as well as CDX1 expression have both been shown to play a role in cell differentiation and cancer (suppression), hitherto only very little has been described with regard to CDX1-associated glycosylation profiles." (PMID 30909444, 2019). "Additionally, HCT116 cells have shown higher levels of cancer stem cells (CSC) and loss of CDX1 expression, whereas induced expression of CDX1 led to reduced clonogenicity and restored the potential of cells for differentiation and lumen formation." (PMID 30909444, 2019). "In addition, it has been suggested that expression of Cdx1 reduces cancer cell proliferation by reducing cyclin D1 expression." (PMID 27092172, 2016). "Investigations on cancer stem cell subgroups in CRC cell lines revealed a higher portion of cancer stem cells in nondifferentiating cell lines such as HCT116, which is accompanied with loss of CDX1 expression and a more aggressive phenotype." (PMID 26537799, 2016). "Further studies in larger series of patients are warranted to elucidate this question and determine the specific role of those cancer associated genes (INPP5A, CDX1, MB, CAMK2A, APOL6 vs. VPS53, FAM57A, GEMIN4, SFRS13, ELP2P, GLOD4, CSF2RA and IL3RA), differentially altered in both groups of tumors." (PMID 21811587, 2011). "Concordantly, the expression of cancer stemness-related genes, such as LGR5 and CD44, was significantly reduced at the mRNA and protein levels in TetOff cells upon expressing wt-Cdx1/2." (PMID 40399276, 2025). "Through VENN analysis, we detected 603 upregulated and 1043 downregulated DEGs overlapping in the three cancer cell lines, including 16 upregulated TFs (e.g., HOXA2, HOXB2, HOXC10, and NKX2-1) and 36 downregulated TFs (e.g., BACH1 and CDX1), respectively." (PMID 32156290, 2020). "Conversely, HDAC1, CCDN1, PCNA, CDX1, KRT18, CDX2 and CASP3 are all expressed at significantly lower levels in normal tissue compared to adenomatous polyp or carcinoma tissues." (PMID 25423035, 2014). "The methylation frequency of each gene ranks with only a few other genes methylated at high frequency in CRC (Cyclin A1, CDX1, RAR-β, MYOD1, p15INK4b and COX-2) in a cancer-specific manner." (PMID 19662090, 2009). "Using the 5 patients with both normal and cancer cells profiled, we estimated the frequency of inactivation of all 56 colon-specific TFs across the 5 patients, which revealed that CDX2 and TRIM31 were inactivated in 80% of the patients, whereas ATOH1, HNF4A, CDX1, and TBX10 were inactivated in 60%." (PMID 33083012, 2020).
inflammation (2 papers, 2018 to 2023). Aberrant reaction of the microcirculation characterized by movement of fluid and leukocytes from the blood into extravascular tissues. "Two components represented chronic inflammation: Chronic Inflammation A consisting of SI (0.44), AAT (0.49), and neopterin (0.50); and Chronic Inflammation B consisting of Cdx1(-0.41), mucin 12 (-0.63), and neopterin (0.62)." (PMID 36809375, 2023). "The intestine specific transcription factors CDX1 and CDX2 are reportedly triggers for metaplastic transition, with differential expression in normal esophageal mucosa compared to metaplasia and CDX2 expression increases with esophageal inflammation." (PMID 30450163, 2018).
CDX1 also shares sentences with these, for which no sentence is quoted: gastric tumors (3 papers); chondrosarcoma (2); endometrial stromal sarcomas (2); oral cancer (2); acute myeloid leukaemia (1); atopic dermatitis (1); C. perfringens infection (1); cholangiocarcinoma (1); chronic lymphocytic leukemia (1); colitis (1); colonic (1); esophageal SCC (1); head and neck squamous cell carcinoma (1); hypertriglyceridaemia (1); hypothyroidism (1); insulinoma (1); intestinal inflammation (1); intestinal type adenocarcinoma (1); lung carcinoma (1); myeloid leukaemias (1); non-small cell lung carcinoma (1); pancreatic cancer (1); pancreatic duct adenocarcinoma (1); seminoma (1); small-intestinal tumor (1).